CD38 (CD38 molecule)
Diseases named in the same sentence as CD38 in open-access papers (continued):
Sharing a sentence is not in itself a finding about the gene and the disease.
multiple myeloma (continued). "Increased sympathetic activation due to both myeloma and active treatment may induce CD38 expression." (PMID 34680206, 2021). "In addition to depleting CD38+ cells, daratumumab also promotes expansion of memory and naïve T-cells, and is approved as monotherapy in patients with multiple myeloma (MM)." (PMID 34177960, 2021). "In this sense, it has also been reported that extramedullary myeloma cells lose the expression of CD38, suggesting that CD38 down-regulation may facilitate the migration of malignant plasma cells to peripheral blood or extramedullary sites." (PMID 32350373, 2021). "Previous retrospective data for patients with multiple myeloma refractory to immunomodulatory agents, PIs, and anti-CD38 monoclonal antibodies from 14 different US academic institutions reported a median progression-free survival (PFS) of only 3−4 months and a median OS of 8−9 months." (PMID 34145225, 2021). "Part B of this phase 1b study (ClinicalTrials.gov number, NCT02283775) evaluated safety and efficacy of a fixed-volume infusion of isatuximab, an anti-CD38 monoclonal antibody, in combination with pomalidomide and dexamethasone (Pd) in relapsed/refractory multiple myeloma patients." (PMID 34050260, 2021). "As an incurable disease for the overwhelming majority of patients, with resistance developing to proteasome inhibitors and other novel drugs including CD38 antibodies, the treatment-refractory state of myeloma portends short survival below 6 months and represents an unmet medical need." (PMID 34071205, 2021). "In addition, CD38 has been identified as a cell-surface marker in hematologic cancers such as multiple myeloma and chronic lymphocytic leukemia and has been shown to play a role in cancer immune tolerance." (PMID 33755743, 2021). "Moreover, a CD38-blocking antibody was found to significantly reduce mitochondrial transfer and mitochondrial oxidative metabolism in myeloma cells cocultured with BM stromal cells." (PMID 34199285, 2021). "CD38 is highly and uniformly expressed in myeloma cells and is an ideal target antigen for MM." (PMID 34513682, 2021). "Furthermore, trials with anti-BCMA CAR-T cells in earlier stages of the disease are ongoing and CAR-T cells targeting other multiple myeloma antigens such as CD38, CD138, and SLAMF7 are also being explored." (PMID 34572927, 2021). "Daratumumab, a CD38 monoclonal antibody, has demonstrated efficacy as monotherapy and combination therapy across several indications, both among newly-diagnosed and refractory patients with multiple myeloma (MM)." (PMID 34772368, 2021). "In MM, osteoclasts can directly inhibit proliferative CD4+ and CD8+ T cells by upregulating immune checkpoint molecules such as programmed death ligand 1 (PD-L1), CD38, and Galectin-9, thus establishing the immunosuppressive microenvironment to protect myeloma cells." (PMID 33553181, 2021). "CD38 is highly expressed in myeloma PCs and activated T cells and NK cells." (PMID 33418913, 2021). "Daratumumab is a CD38-targeted monoclonal antibody that has demonstrated activity as monotherapy and in combination with standard-of-care regimens in patients with relapsed/refractory multiple myeloma (MM) and newly diagnosed MM." (PMID 32457357, 2021). "CD38-targeted antibody, daratumumab, is approved for the treatment of multiple myeloma (MM)." (PMID 32457357, 2021). "Therefore, anti-CD38 antibodies targeting myeloma cells have the potential to restore T cell responses to myeloma cells." (PMID 34199285, 2021). "Despite anti-CD38 directed therapy, quadruplet treatment, higher age and missing deep remission, which correlated negatively with SP-AbT appearance, SP-AbT formation is possible in a majority of myeloma patients after prime-boost vaccination." (PMID 34884200, 2021). "Daratumumab, a novel anti-CD38 mAb approved for r/r multiple myeloma, may be an effective option in the treatment of r/r CD38+ hematological malignancies." (PMID 33807678, 2021).
multiple myeloma (continued). "DARA releases CAM-DR by inhibiting adhesion to BMSCs by internalizing CD38 in myeloma cells." (PMID 33435539, 2021). "In addition, anti-myeloma treatments, and in particular the use of anti-CD38-monoclonal antibodies like daratumumab and isatuximab, are associated with impaired immune response." (PMID 34359701, 2021). "Interestingly, within the bone marrow microenvironment, myeloma cells are protected to CD38 antibody-induced cellular cytotoxicity by upregulating the expression of antiapoptotic molecules such as survivin." (PMID 33727923, 2021). "The anti-CD38 monoclonal antibody daratumumab is approved as a single agent for the treatment of patients with relapsed/refractory multiple myeloma (RRMM) who received at least three prior lines of therapy, including proteasome inhibitor and immunomodulatory agent." (PMID 33763359, 2021). "We find that CD38-inhibitors such as daratumumab, licensed to treat multiple myeloma, and MAP3K12-inhibitors such as CEP-1347 may increase PD risk." (PMID 34930919, 2021). "Aiming to improve the efficacy of treatment of B cell malignancies in general and of multiple myeloma in particular, we evaluated the impact of crosslinking CD38 receptors on the mechanism and extent of apoptotic induction in four CD38 positive malignant B cells (Daudi, Raji, RPMI 8226, and ANBL-6)." (PMID 34361811, 2021). "However, the addition of adjuvants (retinoic acid or interferon-α) to myeloma cells or the inhibition of fratricide using a CD38-blocking nanobody on NK-cells can reverse this balance towards ADCC and thus promote lysis of target cells by ADCC." (PMID 34203012, 2021). "Other studies have suggested that CD38 is only minimally expressed on normal lymphocytes or bone marrow cells, but is highly expressed on the surface of myeloma cells, so the CD38 molecule may be a new target for MM therapy." (PMID 33820568, 2021). "In the bone marrow microenvironment of multiple myeloma, TNT-mediated transcellular transfer of mitochondria from neighboring nonmalignant bone marrow stromal cells to multiple myeloma cells supports oxidative phosphorylation of multiple myeloma cells and is dependent on the expression of CD38." (PMID 34361078, 2021). "Daratumumab is an anti-CD38 monoclonal antibody used for multiple myeloma." (PMID 34956879, 2021). "Highly expressed in almost all myeloma cells, CD38 is an attractive treatment target." (PMID 34752645, 2021). "Consequently, CD38 has gained interest as new molecule for targeted treatment of cancer as recently shown for multiple myeloma." (PMID 34360781, 2021). "The combination therapy was refined with CD16 polymorphism donor selection and uncomplicated novel in vitro pretreatment to avoid undesired fratricide, increasing the in vitro therapeutic effect against the CD-38 positive multiple myeloma cell line by more than 20%." (PMID 33919155, 2021). "Increased expression of CD38 is noted on B-regulatory cells and myeloma-derived suppressor cells." (PMID 34141513, 2021). "Response rates to CD38 mAbs are consistently encouraging in myeloma when combined with current standard of care, even in the relapsed/refractory setting, such that the addition of daratumumab to standard induction therapy (pre-ASCT), and consolidation post-ASCT has recently been reported." (PMID 33777050, 2021). "The ability to target CD38 on the amyloid PC offers new powerful tools to treat AL amyloidosis." (PMID 33806310, 2021). "BCMA expression in myeloma patients is almost universal, but the density of antigen expression in the cell is highly variable and significantly lower as compared to other surface antigens such as CD38." (PMID 33172026, 2020). "Therefore, we further explored the combined effect of targeting PD-1 and CD38 in the endogenously CD38 expressing mouse myeloma J558 tumor model." (PMID 33321969, 2020).
multiple myeloma (continued). "Likewise, multiple myeloma patients who received the anti-CD38 monoclonal antibody daratumumab lost CD38 expression in their tumors which correlated with impaired response." (PMID 32698317, 2020). "Moreover, the Nb-CAR-NK cells effectively depleted CD38-expressing multiple myeloma cells in primary human bone marrow samples." (PMID 32013131, 2020). "Daratumumab, a monoclonal anti-CD38 antibody approved for the treatment of multiple myeloma (MM), was shown to block the delivery of mitochondria to AML cells under both in vitro and in vivo conditions, decrease the oxygen consumption rate (OCR), and inhibit the growth of leukemic cells." (PMID 32635428, 2020). "Finally, the cytotoxic efficacy of Nb-CAR NK-92 cells was tested on primary patient-derived CD38-expressing multiple myeloma cells." (PMID 32013131, 2020). "The efficacy of daratumumab, an anti-CD38 monoclonal antibody, in combination with lenalidomide and dexamethasone or bortezomib and dexamethasone was evaluated in patients with relapsed or refractory multiple myeloma in POLLUX and CASTOR, respectively." (PMID 32143562, 2020). "Daratumumab, anti-CD38 mAb approved for the treatment of multiple myeloma, showed anti-leukemic effects in combination with ponatinib in R/R Ph+ ALL in a single case study and is further investigated in a clinical trial in pediatric and young adult R/R B-ALL (NCT03384654)." (PMID 32806528, 2020). "If we rely primarily on CDC, ADCP, or ADCC for control of myeloma it makes sense to introduce a treatment-free interval, which will allow re-expression of CD38 by the myeloma cells and subsequently, introduce a re-treatment approach where daratumumab is used again in an appropriate new combination." (PMID 32041300, 2020). "New reports suggested that MEDI2228 might synergize with anti-CD38 mAbs or bortezomib to enhance anti-myeloma effect." (PMID 32943087, 2020). "Antibodies targeting CD38 are rapidly changing the treatment landscape of multiple myeloma (MM)." (PMID 32331242, 2020). "Myeloma cells were identified by their high levels of cell surface CD38 (and CD56 or CD319)." (PMID 32013131, 2020). "Approval was based on the results from the STORM study, a Phase II study of selinexor plus dexamethasone in heavily pretreated patients with triple-class refractory multiple myeloma (refractory to an IMiD, a proteasome inhibitor, and an anti-CD38 monoclonal antibody)." (PMID 32992506, 2020). "Furthermore, patient-derived in vitro models demonstrated ADCC as a major therapeutic mechanism of rituximab in non-Hodgkin lymphoma and anti-CD38 antibodies in multiple myeloma." (PMID 32698317, 2020). "Daratumumab, a first in class human monoclonal antibody targeting CD38, is active and well tolerated as a single agent and in combination with standards-of-care in both newly diagnosed and relapsed/refractory multiple myeloma (MM) patients." (PMID 33321969, 2020). "We report the case of a 63-year-old male, diagnosed with a relapsed/refractory multiple myeloma, heavily treated, who expressed strong CD38 marker at the beginning of the treatment, with a posterior negativization of CD38 after four cycles of treatment with daratumumab." (PMID 32399359, 2020). "In addition, many tumor cells, including multiple myeloma, over-express the plasma membrane-associated NAD glycohydrolase CD38, which allows for conversion of extracellular NAD to NAM that can then be used as a precursor for new NAD biosynthesis by the tumor." (PMID 32459815, 2020). "Daratumumab is a CD38 mAb approved for treating R/R and untreated multiple myeloma." (PMID 33292562, 2020). "In this paper we discuss the role of NK cells along with anti-CD38 therapy and their implication in plasma cell dyscrasias, showing that mechanisms triggered by anti-CD38 mAbs ultimately lead to the activation of the immune system against myeloma cell growth." (PMID 32245149, 2020).
multiple myeloma (continued). "Daratumomab (multiple myeloma FDA approval 2015) is a fully human IgG1 mAb targeting CD38 that could have a role in treatment of other CD38-positive B-cell malignancies." (PMID 33271825, 2020). "Daratumumab is an FDA-approved monoclonal antibody therapy for multiple myeloma that targets CD38." (PMID 33142671, 2020). "The CD38-targeting antibody daratumumab mediates its anti-myeloma activities not only through Fc-receptor-dependent effector mechanisms, but also by its effects on T-cell immunity through depletion of CD38+ regulatory T-cells, regulatory B-cells, and myeloid-derived suppressor cells." (PMID 33321969, 2020). "Indeed, with daratumumab for example, the release of CD38 from MM cells by microvesicles and the transfer of CD38–daratumumab complexes from myeloma cells to monocytes and granulocytes have been reported." (PMID 32512883, 2020). "Third, future preclinical and clinical studies are warranted to assess the therapeutic efficacy of CD38-specific hcAbs in combination with other anti-MM agents and the efficacy in myeloma cell lines and patient cells resistant to conventional or novel therapies." (PMID 32194826, 2020). "A recent pre-clinical observation may lend further support to the notion that low expression of CD38 by myeloma cells may in fact be beneficial." (PMID 32041300, 2020). "In addition to targeting myeloma cells, the anti-CD38 antibody, daratumumab, also depletes CD38(+) regulatory cells in the bone marrow thus promoting an immune response." (PMID 33634031, 2020). "This is demonstrated by the recent observation that bone marrow stromal cells influence the myeloma growth through the process of intercellular mitochondrial transfer, which is made physically possible by tumor-derived tunneling nanotubes, where CD38 also plays a role." (PMID 33322499, 2020). "A puzzling observation from the GEN501 and Sirius trials is that many patients may continue to respond to daratumumab even when the CD38 expression by myeloma cells is low." (PMID 32041300, 2020). "It has also been proposed that pharmacological manipulation of the expression of CD38 by myeloma cells may tip the balance in favor of a better response to daratumumab." (PMID 32041300, 2020). "While the majority of in vitro and in vivo observations have been done in MM, initial experiences might be a launching pad for expanding research on the use of anti-CD38 target therapy in AL amyloidosis." (PMID 32531894, 2020). "Each of these three anti-CD38 MoAbs provided a strong case for being used in AL amyloidosis." (PMID 32531894, 2020). "Target therapy with anti-CD38 MoAbs in AL amyloidosis could be revealed to be the most appropriate strategy, even when given alone, to reduce the adverse effects in these fragile patients, maybe at a personalized dose, and perhaps for a more prolonged time." (PMID 32531894, 2020). "Moreover, the initiallyavailable experiences with the anti-CD38 MoAb DARA in AL amyloidosis are reviewed." (PMID 32531894, 2020). "In addition, CD38 cytotoxic antibodies has been used to treat CD38 positive tumors such as multiple myeloma and potentially CLL." (PMID 31214171, 2019). "Another mechanism involves the degradation of the antigen–antibody complex or the rapid elimination of myeloma cells expressing high levels of CD38, as demonstrated by the fact that MM CD38 levels were only reduced in the presence of complement or effector cells." (PMID 31847204, 2019). "Additionally, the tumor microenvironment protects myeloma cells from CD38 antibody induced ADCC by upregulating anti-apoptotic proteins, such as survivin." (PMID 31569769, 2019). "The role of CD38 in multiple myeloma and CLL has been studied extensively, igniting the development of numerous treatment strategies to specifically target malignant cells while attempting to spare those normal cells that rely on CD38 expression for functional activity." (PMID 31878283, 2019).
multiple myeloma (continued). "Based on similar results with an anti-CD38 antibody in myeloma and CSL362 with HL, we infer that our observation of the involvement of ARF6–PLD-1 may be generally applicable in NK-mediated ADCC." (PMID 30647406, 2019). "Taken together, the multitude of available CD38-targeting agents that exhibit efficacy in myeloma and other CD38+ malignancies need to be studied extensively in the solid tumor field in order to identify which tools will provide the best anti-tumor response in solid tumors." (PMID 31878283, 2019). "Since adenosine exerts an immunosuppressive activity, as observed in the bone marrow niche in multiple myeloma, targeting CD38 with daratumumab may also boost host-antitumor immune response, although these preliminary observations need to be confirmed." (PMID 31892266, 2019). "Anti-CD38 monoclonal antibodies are shown to be highly efficacious in the treatment of multiple myeloma (MM) and pre-clinical studies highlight the potential use in other tumors such as CLL, lung cancer, prostate cancer and melanoma and in a preclinical model of melanoma." (PMID 31214171, 2019). "Evidence of high CD38 expressing Treg have been reported for multiple myeloma and acute lymphoblastic leukemia, where the use of mAbs against CD38 (daratumumab, isatuximab, and MOR202) is more than a promising therapeutic option to reestablish a functional immune surveillance." (PMID 31402913, 2019). "This inventive strategy demonstrated clear efficacy in multiple models of myeloma, but may also present an opportunity for the treatment of solid tumors which rely on normal CD38-expressing immune cells for tumor cell elimination." (PMID 31878283, 2019). "Similarly, CD38 CAR T cells have been developed for the targeting of CD38+ multiple myeloma cells, but on-target/off-tumor effects limited its efficacy; thus, the development of lower potency CD38 CAR T cells has improved specific on-tumor effects." (PMID 31878283, 2019). "Anti-CD38 monoclonal antibodies, such as daratumumab, have been previously demonstrated to induce a substantial depletion of plasma cells in the bone marrow of patients with refractory multiple myeloma, and are currently used in clinical practice." (PMID 31892266, 2019). "In addition, the surface expression of CD38 in myeloma cells is reduced after daratumumab exposure due to the transfer of CD38-daratumumab complexes from myeloma cells to monocytes and granulocytes by a process called trogocytosis." (PMID 31766279, 2019). "This could be a possibility, as similar results were obtained with daratumumab treatment in terms of suppressing CD38+ Tregs and MDSCs in myeloma." (PMID 31878283, 2019). "Daratumumab, an anti-CD38 antibody, is currently in the clinical trials for multiple myeloma." (PMID 31118070, 2019). "In the last decades CD38 has emerged as an attractive target for multiple myeloma (MM)." (PMID 31847204, 2019). "Indeed, DPP8 was expressed at a higher level in CD38+ bone marrow cells of Waldenstrom’s macroglobulinemia and multiple myeloma patients than those of healthy volunteers." (PMID 31792328, 2019). "Interestingly, CD38, a well-studied target for multiple myeloma, has been less focused on as a target for AML." (PMID 31434267, 2019). "However, some concerns have been recently raised by the finding that, in a myeloma setting, anti-CD38 ligation by specific antibodies on malignant plasma cells leads to the aggregation, polarization and release of EVs derived from cell membrane." (PMID 31783629, 2019). "In addition, based on the results obtained in MM patients, the efficacy and safety of anti-CD38 MoAb are now being evaluated in other plasma cell dyscrasias such as smoldering MM and in immunoglobulin light-chain amyloidosis." (PMID 31842517, 2019). "Therefore, after confirming that approximately 75% of CD34+ mobilized peripheral blood progenitor cells from myeloma patients en route to SCT co-expressed CD38, we sought to determine the number of CD38 molecules per CD34+ cell." (PMID 30356940, 2018).